TIMP1 (TIMP metallopeptidase inhibitor 1)
Diseases named in the same sentence as TIMP1 in open-access papers (continued):
Sharing a sentence is not in itself a finding about the gene and the disease.
autism (1 paper, 2024). Persistent deficits in social interaction and communication and interaction as well as a markedly restricted repertoire of activity and interest as well as repetitive patterns of behavior. "Dipk2b has been reported to alter neuronal cellular secretory pathways that are involved in autism while RAB37 is known to participate in membrane trafficking and in the regulation of TIMP1 exocytosis." (PMID 38351172, 2024).
autoimmune inner ear disease (1 paper, 2022). A syndrome characterized by rapidly progressive sensorineural hearing loss (SNHL), that is often bilateral, and is potentially reversible. "In addition, the balance of MMP9 and TIMP1 expression is thought to affect inflammation and corticosteroid response in patients suffering from autoimmune inner ear disease." (PMID 35573665, 2022).
Autoimmunity (1 paper, 2005). The occurrence of an immune reaction against the organism's own cells or tissues. "Antibodies against TIMP-1 and TIMP-2 comprised most of the anti-TIMP directed autoimmunity." (PMID 16207317, 2005).
B-cell neoplasm (1 paper, 2019). A group of heterogeneous lymphoid tumors generally expressing one or more B-cell antigens or representing malignant transformations of B-lymphocytes. "The antiapoptotic role of TIMP-1, which may contribute to the poor prognosis of aggressive B-cell neoplasms, is determined by the binding of TIMP-1 to a putative cell-surface receptor, independent of its MMP inhibitory function." (PMID 31934533, 2019).
benign meningioma (1 paper, 2024). A grade I, slowly growing meningioma. "Consistent with previous results, we confirmed a higher expression of TIMP1 and TIMP2 in the benign meningioma group." (PMID 38474106, 2024).
brain cancer (1 paper, 2020). A primary or metastatic malignant neoplasm affecting the brain. "TIMP1 expression is often remarkably enhanced in the in the late stages of such tumors, in addition to in patients with endometrial, breast or brain cancer who have a shorter time prior to relapse." (PMID 32420905, 2020).
brain glioma (1 paper, 2024). A malignant glioma that involves the brain. "TIMP-1 also affects the localization and differentiation of neural stem cells by acting as a chemoattractant to neural stem cells in brain glioma through CD63 binding." (PMID 39329731, 2024).
buccal mucosa cancer (1 paper, 2013). "RT-PCR and western blot analyses were conducted to determine whether metastasis in the buccal mucosa cancer model was a result of gene regulation of metastatic mediators, specifically MMPs (MMP-2 and MMP-9) and TIMPs (TIMP-1 and TIMP-2)." (PMID 23599733, 2013).
Campylobacter enteritis (1 paper, 2018). "In conclusion, after human Campylobacter enteritis, the serum levels of MMP-8, MMP-9 and their regulators MPO, HNE and TIMP-1 are elevated as compared to the serum levels of healthy controls." (PMID 30551610, 2018).
cardiac arrest (1 paper, 2026). Cessation of breathing and/or cardiac function. "Out-of-hospital cardiac arrest (OHCA) leads to an inflammatory response, including alterations in matrix metalloproteinase (MMP)-9 and tissue inhibitor of matrix metalloproteinase (TIMP)-1 concentrations." (PMID 41503448, 2026). "To extend the knowledge on the temporal evolution of MMP-9 and TIMP-1 concentrations after cardiac arrest, we analysed MMP-9 and TIMP-1 concentrations from admission and compared the levels between OHCA patients and patients with cardiovascular disease burden without cardiac arrest." (PMID 41503448, 2026).
cervical spondylosis (1 paper, 2012). "These TIMP protein findings are not in agreement with those reported by Le Maitre and colleagues; however, they do corroborate those by Kanemoto and colleagues where 78.1% of cervical spondylosis and 93.3% of lumbar spondylosis specimens were MMP-3 positive and TIMP-1 negative." (PMID 22394620, 2012).
choledocholithiasis (1 paper, 2022). Presence or formation of gallstones in the common bile duct. "A study found that TIMP-1 and MMP-9 are differentially expressed in the bile of patients with CCA and choledocholithiasis, but they have low diagnostic specificity and accuracy and, thus, are possible but less likely to serve as a diagnostic marker of CCA." (PMID 36010914, 2022).
choriocarcinoma (1 paper, 2025). An aggressive malignant tumor arising from trophoblastic cells. "Choriocarcinoma is associated with MARCKS, DAB2, ENPEP, and TIMP1." (PMID 40565366, 2025).
chorioretinal disease (1 paper, 2020). "Our study design does not allow conclusions on whether or not MMP-9 vs. TIMP-1 imbalances play a role in local chorioretinal disease development—but only that a general imbalance in extracellular matrix homeostasis is not present in Caucasians with PCV." (PMID 32429088, 2020).
chronic lung disease (1 paper, 2018). According to the definitions of the American and British Thoracic Societies, including pulmonary functional tests, X-rays, and CT scans for items such as fibrosis, bronchiectasis, bullae, emphysema, nodular or lymphomatous abnormalities. "TIMP1 is an inhibitor of Matrix metallopeptidase 9 (MMP9), which plays an important role for variety of homeostatic functions and elicit repair responses as balance mechanisms in many chronic lung diseases like COPD." (PMID 29716632, 2018).
cleft palate (1 paper, 2019). Cleft palate is a fissure type embryopathy that affects the soft and hard palate to varying degrees. "While MMP and TIMP expressions appear to be critical throughout all stages of palatal development, knockout mice for Timp1, Timp2, Timp3, Timp4, Mmp2, Mmp9, Mmp13, Mmp14, Mmp16, and Mmp25 do not develop cleft palate." (PMID 31921852, 2019).
collagenous colitis (1 paper, 2013). A type of microscopic colitis of unknown etiology. "In a murine model of intestinal fibrosis, TIMP-1, which is upregulated, effectively inhibited ECM degradation by MMPs, and TIMP-1 was found to be increased in collagenous colitis and in CD strictures." (PMID 23834907, 2013).
complication (1 paper, 2015). Any disease or disorder that occurs during the course of, or because of, another disease, treatment, or procedure. "Levels of HbA1c, LDL, triglycerides, MMP-1, MMP-2, MMP-3, MMP-9, MMP-10, TIMP-1 and markers of LGI and ED were significantly higher in individuals with vascular complications compared to those without." (PMID 25848912, 2015).
corneal ulcer (1 paper, 2021). Area of epithelial tissue loss from corneal surface; associated with inflammatory cells in the cornea and anterior chamber. "Also, an injury without bacterial infection resulted in an increase in both MMP-2 and−9 and a slight but significant downregulation of TIMP-1 in mouse corneal ulcer." (PMID 33816586, 2021).
coronary artery stenosis (1 paper, 2022). "For instance, in patients with coronary artery stenosis, serum levels of TIMP-1 were reported to exhibit a correlation with the incidence of major adverse cardiac events, and, thus, the prognosis in these patients." (PMID 35628490, 2022).
diverticulitis (1 paper, 2024). An infection that develops in the diverticula of the intestinal tract. "Whilst a collagen deficit does not identify individuals who will go on to develop diverticulitis, one study demonstrated downregulation of MMP2, MMP9 and MMP13 expression and an increase in MMP1, TIMP1 and TIMP3 in inflamed mucosa of patients with diverticulitis versus Crohn’s disease." (PMID 38831715, 2024).
diverticulosis (1 paper, 2025). "The genes regulating ECM turnover, including TIMP1, MMP3, and MMP9, are involved in diverticulosis development." (PMID 40428403, 2025).
encephalomyelitis (1 paper, 2023). Inflammation of the brain and the spinal cord. "Surprisingly, infected PKR−/− mice revealed novel positive regulatory effects of PKR on tissue inhibitor of metalloproteinases inhibitor 1 (Timp-1), Il-21, and Il-10 mRNA expression, all prominently associated with CD4 T cells during MHV-JHM v2.2-1 encephalomyelitis." (PMID 38140641, 2023).
endocarditis (1 paper, 2021). Inflammation of the endocardium. "Interestingly, higher MMP-8 and TIMP-1 levels were associated to presence of a deep infection focus but not to endocarditis." (PMID 34043679, 2021).
endotoxemia (1 paper, 2018). "Additionally, it has been observed to upregulate hepatocyte growth factor (HGF) and matrix metalloproteinases (MMPs), downregulate tissue inhibitor of metalloproteinase 1 (TIMP-1), reduce portal pressure, bacterial translocation and endotoxemia." (PMID 29702590, 2018).
esophageal squamous cell carcinoma (1 paper, 2022). Esophageal squamous cell carcinoma (ESCC) is a type of esophageal carcinoma (EC) that can affect any part of the esophagus, but is usually located in the upper or middle third. "The aim of the study was to explore the diagnostic values of anti-POSTN and anti-TIMP1 autoantibodies in esophageal squamous cell carcinoma (ESCC)." (PMID 35559040, 2022).
Ewing sarcoma (1 paper, 2022). A small round cell tumor that lacks morphologic, immunohistochemical, and electron microscopic evidence of neuroectodermal differentiation. "But TIMP1 was reduced expression in Ewing's sarcoma tissues than normal tissues." (PMID 35578666, 2022).
exanthem subitum (1 paper, 2022). "In addition, HHV-6 and -7, which are causative viruses of exanthem subitum, infect several immunocytes, including monocytes/macrophages and CD4+ T cells, the latter of which have been identified as a candidate secreting TIMP-1 in vitro." (PMID 36670630, 2022).
extramedullary plasmacytoma (1 paper, 2023). "TIMP1 mRNA levels are also markedly higher in extramedullary plasmacytoma than in BM plasma cell in corresponding patients." (PMID 36768545, 2023).
Fever (1 paper, 2023). Body temperature elevated above the normal range. "The concentration of MMP-2, MMP-3, MMP-9, MMP-13, TIMP-1, and FG-α in the KD group were significantly higher than those in the fever group (p < 0.05)." (PMID 37575991, 2023). "The concentration of MMP-2, MMP-3, MMP-9, MMP-13, TIMP-1, and FG-α in the KD group were significantly higher than those in the fever group (p < 0.05).The KD group was divided into two subgroups, patients with combined CAL and 179 patients without combined CAL." (PMID 37575991, 2023). "Red blood cell count (RBC) and hemoglobin (Hb) levels were significantly decreased (p < 0.05).The concentration of serum MMPs, TIMP-1, and FG-α in the KD and fever groups were significantly higher than those in the normal group (p < 0.05)." (PMID 37575991, 2023).
Fibroadenoma (1 paper, 2025). A benign tumor of the breast characterized by the presence of stromal and epithelial elements. "KRT5, TGF-β, PAI-1, HIF-1α, TIMP1, MMP2, TWIST1, VEGFα, and BRCA2 were all significantly upregulated in fibroadenomas." (PMID 40806434, 2025). "TIMP1 displayed significant expression among cancer samples in the Control group and healthy breasts (regardless of group), as well as between fibroadenoma cases in the diet group and healthy breasts (independent of the group)." (PMID 40806434, 2025).
follicular thyroid carcinoma (1 paper, 2013). "Interestingly, the observed increase of serum TIMP-1 concentrations seems to be independent of TSP-1, even though there is some evidence that TSP-1 induced expression of TIMP-1 in follicular thyroid carcinoma cells." (PMID 23919647, 2013).
Fulminant hepatitis (1 paper, 2009). Acute hepatitis complicated by acute liver failure with hepatic encephalopathy occurring less than 8 weeks after the onset of jaundice. "The plasma concentrations of the final two elevated cytokines (TIMP-1 and TNF-α) are significantly increased in patients with fulminant hepatitis, reflecting severe hepatic inflammation." (PMID 19317920, 2009).
gastroenteritis (1 paper, 2018). An inflammatory disorder that affects the upper and lower gastrointestinal tract. "In a study on childhood gastroenteritis, two Campylobacter and four Salmonella patients were included and showed elevated serum concentrations of MMP-9 and TIMP-1 as compared to healthy controls." (PMID 30551610, 2018).
gastrointestinal mucositis (1 paper, 2022). "Therefore, by degrading extracellular matrix proteins, MMPs and TIMP-1 clearly exert damaging effects on tissues and are crucial to the pathophysiology of gastrointestinal mucositis." (PMID 36290656, 2022). "Our study has demonstrated that gastrointestinal mucositis induced by 5-FU increases the activity of the proteolytic enzymes MMP-1, MMP-2, MMP-8, and TIMP-1 in sera and tissues." (PMID 36290656, 2022).
geographic atrophy (1 paper, 2021). "Recent studies demonstrate significant differences in plasma concentrations of MMP-9, TIMP-1, and TIMP-3 proteins in patients with AMD: higher levels of TIMP-1 and MMP-9 in patients with geographic atrophy (GA) and lower levels of TIMP-3 and lower TIMP-3/MMP-2 ratios in patients with CNV." (PMID 35155457, 2021).
giant cell arteritis (1 paper, 2021). "In a recent study, TIMP-1 was identified as a potential marker of active giant cell arteritis (GCA)." (PMID 34940542, 2021).
granulomatosis with polyangiitis (1 paper, 2021). A small-vessel necrotizing vasculitis characterized by the association of inflammation of the vessel wall and peri- and extravascular granulomatosis. "In the present study, we investigated whether TIMP-1 is clinically useful as a predictor of relapse and sustained remission in AAV patients with microscopic polyangiitis (MPA) and granulomatosis with polyangiitis (GPA) during maintenance therapy." (PMID 33743769, 2021).
Graves disease (1 paper, 2025). Graves' disease is an autoimmune disorder that leads to overactivity of the thyroid gland (hyperthyroidism).It is caused by an abnormal immune system response that causes the thyroid gland to produce too much thyroid hormones. "In a recent study by our team, low global strain values were found in both hypothyroid and euthyroid patients with Graves’ disease and were correlated with TIMP-1." (PMID 40095713, 2025).
H. pylori (1 paper, 2012). "The MMP and TIMP-1 expressions in the combined H. pylori-infection and NSAID-use group were between the other groups." (PMID 22645431, 2012).
Hashimoto thyroiditis (1 paper, 2025). An autoimmune disorder caused by the production of autoantibodies against thyroid tissue. "In conclusion, Hashimoto’s thyroiditis is associated with impaired segmental and global longitudinal LV strain, and this impairment is correlated with TIMP-1 and anti-TPO levels, indicating the involvement of cardiac tissue beyond the thyroid gland." (PMID 40095713, 2025).
hemangiosarcomas (1 paper, 2010). "TIMP-1 expression was estimated to be, on average, 7 fold higher in hemangiosarcomas than in splenic hematomas based on microarray data, whereas RT-qPCR showed changes as large as +800 fold." (PMID 21062482, 2010).
hemarthrosis (1 paper, 2021). Bleeding into the joints. "Higher levels of SF MMP-3 and TIMP-1 also associated with the presence of hemarthrosis (moderate or severely blood-stained SF) and the severity of injury." (PMID 33671471, 2021).
hematoma (1 paper, 2020). A hematoma is a collection of blood from a vascular structure into an extravascular space. "When we combined the results from the two cohorts, we observed a statistically significant association between TIMP-1 and hematoma volume (Overall β = 0.14, 95% CI = 0.08–0.21)." (PMID 32587306, 2020). "In CHN, TIMP-1 was associated with admission-hematoma volume and MMP-7 was elevated in patients with deep when compared to lobar hematoma." (PMID 32587306, 2020). "In this study, we report that TIMP-1 is significantly associated with hematoma volume in two independent cohorts, and after a combined meta-analysis, suggesting that TIMP-1 might be potential critical biomarker in ICH." (PMID 32587306, 2020). "Therefore, the association of TIMP-1 with hematoma volume in two independent ICH cohorts suggests its potential as ICH biomarker." (PMID 32587306, 2020). "In VdH, admission-hematoma volume was associated with TIMP-1 and MMP-7." (PMID 32587306, 2020). "We report for the first time that circulating TIMP-1 is associated with hematoma volume in two independent ICH cohorts and when we combined the results from both cohorts suggesting the potential of TIMP-1 as biomarker for ICH." (PMID 32587306, 2020). "In this study, we explored the plasmatic levels of several MMPs and TIMP-1 and their relationship with hematoma volume and location as well as with other clinical, radiological and functional variables in two independent cohorts of ICH patients." (PMID 32587306, 2020).
hereditary gingival fibromatosis (1 paper, 2024). Hereditary gingival fibromatosis (HGF) is a rare benign, slowly progressive, non-inflammatory fibrous hyperplasia of the maxillary and mandibular gingivae that generally occurs with the eruption of the permanent (or more rarely the primary) dentition or even at birth. "Decreased MMP1, but not TIMP1, production was indeed previously associated with hereditary gingival fibromatosis (HGF), a genetically heterogeneous condition characterized by pathological fibrosis of gingival tissue and abundant production of type I collagen and VIM91." (PMID 38664418, 2024).
Hernia (1 paper, 2013). "Moreover, as supported by the literature, several have been associated with hernia formation, Ehlers–Danlos syndrome, and Marfan’s syndrome (e.g., COL1A1, COL3A1, COL5A1, FBN1, and TIMP1)." (PMID 22648066, 2013).
histiocytic sarcoma (1 paper, 2021). An aggressive malignant neoplasm with a poor response to therapy, usually presenting as stage III/IV disease. "It has been shown previously that spontaneous canine histiocytic sarcomas exhibited an expression of MMPs and TIMP-1, mainly at the invasive front of the neoplasms and within tumor-associated macrophages." (PMID 33808256, 2021).
Hodgkins lymphoma (1 paper, 2021). A heterogeneous group of malignant lymphoid neoplasms of B-cell origin characterized histologically by the presence of Hodgkin and Reed-Sternberg (HRS) cells in the vast majority of cases. "Specifically, TIMP-1 can act as a growth factor in many types of cells, such as those seen in Hodgkin’s lymphoma." (PMID 34204115, 2021).
hydronephrosis (1 paper, 2020). Collection of urine in the renal pelvis that results in dilatation of the renal pelvis and calyces. "This study evaluates serum and urinary metalloproteinases MMP-1, MMP-2, and MMP-9 and tissue inhibitors of metalloproteinases TIMP-1 and TIMP-2 as potential biomarkers of ON in children with congenital unilateral hydronephrosis (HN) caused by UPJO." (PMID 32670438, 2020).
hyperaldosteronism (1 paper, 2015). Overproduction of aldosterone by the adrenal glands, which may lead to hypokalemia and/or hypernatremia. "Although we found a positive correlation between PAC and MMP-9/TIMP-1 ratio,hyperaldosteronism is known to be an independent risk factor in arterial hypertensionand, thus, in the process of arterial stiffening." (PMID 26039662, 2015).
Hyperinsulinemia (1 paper, 2019). An increased concentration of insulin in the blood. "The TIMP1 (TIMP Metallopeptidase Inhibitor 1) gene participates in the inhibition of the insulin signaling mechanism and its product levels were shown to increase as a result of hyperinsulinemia." (PMID 31138121, 2019).
hyperuricemia (1 paper, 2023). An abnormally high level of uric acid. "Given that anserine decreased the expression of TLR4/MyD88/NF-κB and NLRP3 and elevated Nrf2 and TIMP1 in hyperuricemic rats, we speculate that anserine improves overall kidney function by decreasing inflammation, oxidative stress and cellular damage in hyperuricemia." (PMID 36839325, 2023).
Hypothermia (1 paper, 2012). Reduced body temperature due to failed thermoregulation. "A time dependent increase was pronounced in group T. Hypothermia reduced increase of TIMP-1 and showed significantly lower levels after 4 and 24 hours compared group T (p < 0.01)." (PMID 22397464, 2012).